PDPN (podoplanin)
Diseases named in the same sentence as PDPN in open-access papers (continued):
Sharing a sentence is not in itself a finding about the gene and the disease.
cancer (continued). "The study’s findings showed that the lung tumor formation was increased with overexpression of PDPN and was independent of the number of injected cancer cells." (PMID 39403603, 2024). "A novel CasMab against PDPN, PMab-117-mG2a possesses a superior reactivity to cancer cells, but not to normal cells." (PMID 39594582, 2024). "The interaction of PDPN and CLEC-2 is a target for cancer treatment." (PMID 38504248, 2024). "This resistance may be mediated by the secretion of hepatocyte growth factor (HGF) by PDPN-positive CAFs, which activates the mesenchymal-epithelial transition (MET) signaling pathway and promotes cancer cell survival and growth." (PMID 39403603, 2024). "As AC invades deeper, the CAFs surrounding the carcinoma cells become dominated by PDPN-negative cells, representing advanced-stage CAFs." (PMID 39451200, 2024). "Furthermore, biological agents targeting PDPN, including antisera and CAR‐T cells, have been shown to suppress cancer development in preclinical studies." (PMID 36156321, 2023). "The PDPN expression values in 33 kinds of cancers were extracted from TCGA database and compared with the PDPN expression values in the tissues of non-lesion sites obtained from GTEx database of each cancer type." (PMID 36434176, 2023). "Notably, CAFs expressing podoplanin enhance the local invasion of cancer cells owing to invasion into the collagen matrix, and inhibition of ROCK signaling by podoplanin knockdown in CAFs decreases the invasion ability of CAFs." (PMID 36376711, 2023). "Therefore, circITGB6 expression is positively correlated to PDPN abundance in a mouse liver metastatic model of CRC and human cancer biopsies." (PMID 37898647, 2023). "Like PDPN, serum/glucocorticoid-regulated kinase 1 (SGK1, lfc = −2.86), listed among the top 10 genes downregulated by QUE pre-treatment, is known to play a crucial role in tumourigenesis and cancer progression." (PMID 37755981, 2023). "Recent studies have shown that in various pathological skin conditions, including inflammatory diseases and cancers, podoplanin is upregulated in cells that do not normally express podoplanin and contributes toward disease development and progression." (PMID 35163233, 2022). "In contrast, in RAMP3-/- mice, PDPN-negative benign CAFs predominates, resulting in a decrease in cancer malignancy." (PMID 35625516, 2022). "The intracellular domain of podoplanin consists of just nine amino acids; however, ezrin/radixin/moesin (ERM) proteins can bind to the juxtamembrane region, leading to RhoA protein activation and epithelial-mesenchymal transition (EMT) in cancer cells." (PMID 35163233, 2022). "We successfully transduced cancer-specific CAR on human T cells by lentivirus-mediated expression and demonstrated that the engineered T cells were specific and effective against cancer-specific PDPN-positive cells." (PMID 35991754, 2022). "This study demonstrated that Ki-67/podoplanin double immunostaining expression correlated with the histopathological grade of HNSCC, suggesting that these markers are reliable in the clinical use and prognosis of cancer patients." (PMID 36077194, 2022). "In the present study, well-differentiated carcinoma showed no expression and less differentiated carcinomas showed diffuse expression of podoplanin." (PMID 36247509, 2022). "Calretinin, D2-40 (podoplanin), Wilms’ tumor-1 (WT1) and CK5/6 are recommended for distinguishing mesothelial differentiation, whereas the common markers of carcinoma are BerEP4, CEA (carcinoembryonic antigen), pancytokeratins and, more recently, claudin-4 as a marker of adenocarcinoma." (PMID 35205798, 2022). "Moreover, platelet-derived TGFβ upregulated PDPN expression in human bladder cancer cells, which induced EMT process and cancer cell invasion." (PMID 34987523, 2021). "Therefore, inhibiting the interaction between PDPN and CLEC-2 is believed to be a unique, and feasible treatment strategy for targeting metastasis of the cancer cells." (PMID 32858947, 2020).
cancer (continued). "Podoplanin and CD44 are transmembrane glycoproteins involved in inflammation and cancer." (PMID 33003440, 2020). "Particularly interesting for therapeutic purposes is the LpMab series recognizing cancer-specific aberrant glycosylated podoplanin, which reacts only with podoplanin expressed in tumors and not with podoplanin in normal cells." (PMID 30736372, 2019). "The results of several studies have shown that PDPN is involved in ECM remodeling, and that the process of ECM degradation predominantly involves MMP-2 and MMP-9 whose expression correlates with prognosis in some cancer types." (PMID 30654768, 2019). "Our results demonstrate that both CDH3 and PDPN are activated in advanced stage LSCC, suggesting that LSCC cancer cells may induce collective migration (CCM) to invasion and metastasis." (PMID 31217907, 2019). "THBS4 is expressed on stromal cells with αSMA or Podoplanin expression in the GC microenvironment, but not expressed on cancer cells with cytokeratin expression." (PMID 31703077, 2019). "Since cancer cells may interfere with physiological interaction between PDPN and CLEC-2, targeting the PDPN and CLEC-2 interaction seems to be a reasonable cancer treatment." (PMID 31208371, 2019). "Patients with higher populations of podoplanin-positive CAFs exhibit worse outcomes after GFT treatment; this finding was supported by the observation of increased ERK1/2 pathway activity in GFT-treated cancer cells cocultured with podoplanin-positive CAFs." (PMID 30927928, 2019). "It is reported that NZ-1 and MS-1 inhibit PDPN-CLEC-2 interaction in vitro, but whether these antibodies suppress human cancer growth and/or metastasis remains unknown." (PMID 31208371, 2019). "Podoplanin, introduced in the paragraph about SCC, is another researched molecule believed to play different roles in the EMT of some cancers, by losing epithelial-specific markers such as E-cadherin and gaining mesenchymal markers, among which are N-cadherin and fibronectin." (PMID 31934531, 2019). "PDPN is a widely-accepted marker of CAFs, which was highly expressed in gastric fibroblasts but absent in cancer cells." (PMID 30038550, 2018). "In surgically resected human SCLC specimens, the frequency of Geminin-positive cancer cells was significantly higher in the cases with PDPN-positive CAFs than in the cases with PDPN-negative CAFs." (PMID 25909164, 2015). "To verify the in vitro results, we examined the frequency of Geminin-positive cancer cells in cases with PDPN-positive CAFs and those with PDPN-negative CAFs among surgically resected SCLC specimens." (PMID 25909164, 2015). "It is hypothesized that podoplanin is likely to be important in the process of EMT, as a number of cancer cells in ESCC co-expressed podoplanin and vimentin." (PMID 26095281, 2015). "Thus, podoplanin has a key role in the regulation of invadopodia function in SCC cells, controlling the initial steps of cancer cell invasion." (PMID 25486435, 2015). "LpMab-2 reacted with podoplanin-expressing cancer cells but not with normal cells; therefore, LpMab-2 is an anti-podoplanin CasMab that is expected to be useful for molecular targeting therapy against podoplanin." (PMID 25080943, 2014). "All these results are not sufficient enough to support that CD133 or podoplanin can detect cancer stem cells in ACC." (PMID 24804195, 2014). "A cell surface transmembrane glycoprotein, podoplanin, has been shown to regulate migration, epithelial-to-mesenchymal transition (EMT), and metastasis of cancer cells, and its expression is often related to malignancy and poor outcome in MPM and many other cancers." (PMID 24690739, 2014). "Podoplanin (PDPN) is a lymphatic vessel marker (D2-40), and expression of PDPN by stromal CAFs has been reported to be a prognostic indicator in various types of cancer." (PMID 24354864, 2013).
cancer (continued). "Despite no detection of PDPN in culture supernatants of CAFs (data not shown), PDPN+ CAFs had a promoting effect on cancer cell invasion in the indirect co-culture system." (PMID 24354864, 2013). "PDPN+ fibroblasts (≥30%) were observed in 70.5% (74/105) of pancreatic IDCs, but no PDPN+ cancer cells were observed." (PMID 24354864, 2013). "Well-differentiated carcinomas did not express podoplanin, whereas moderately differentiated carcinomas expressed podoplanin exclusively in the invading front." (PMID 17179989, 2007). "In addition to their functions in cancer progression, CD9 and CD44 are differentially expressed by specific lymph node stromal cell populations and can both suppress podoplanin-dependent contractility and contribute toward lymph node expansion during adaptive immune activation." (PMID 35163233, 2022). "LpMab-2 (Lp2) reacted with PDPN-expressing cancer cells but not with normal cells." (PMID 35991754, 2022). "Lp2 can react with PDPN-expressing cancer cells but not with normal cells, such as mesothelium." (PMID 35991754, 2022). "Podoplanin is a transmembrane O-glycosylated mucin-type protein that is expressed on type I lung epithelial cells, fibroblastic reticular cells, lymphatic endothelial cells, and podocytes and is increased on inflammatory macrophages, TH17 cells, fibroblasts, and cancer cells." (PMID 35082906, 2022). "Comparative profiling of spheroids from ascites and outgrowing adherent cancer cells revealed a transcriptional switch that resembled mesenchymal–epithelial transition, but unexpectedly also included induction of the mesothelial markers calretinin (CALB2) and podoplanin (PDPN)." (PMID 32533757, 2020). "However, in the study conducted by Kato and Kaneko, the authors succeeded in developing a cancer-specific antibody, which is known as the cancer-specific monoclonal antibody (CasMab), thereby adding a sense of feasibility to the actual use of CAR T cell therapies that can specifically target PDPN." (PMID 32858947, 2020). "This study supports that PDPN could be a useful of better prognostic maker and indicates better differentiation for LUSC patients, and the value of PDPN expression as a marker for cancer stem cells in LUSC should be critically evaluated in future studies." (PMID 32408907, 2020). "However, only recently has the concept of ‘cancer‐associated pericytes’ (CAP) been coined to designate FAP+ perivascular cells, which were phenotypically distinguishable from CAF by the absence of podoplanin." (PMID 32767843, 2020). "To functionally evaluate the specific role of lymphatic vessels in cancer progression and metastasis, we generated novel transgenic mice that express the herpes simplex virus (HSV) thymidine kinase (tk) under the control of the PDPN gene promoter (PDPN-tk mice)." (PMID 30592710, 2018). "In terms of the staining patterns of palladin, α-SMA, and podoplanin, palladin-stained stromal cells and podoplanin-stained cells were mainly located near cancer cells, though podoplanin-stained cells were distributed to a wider area independent of cancer cell distribution." (PMID 27023252, 2016). "CAFs-PDPN did not affect the number of dead cancer cells (7-AAD-positive cancer cells, P = 0.59)." (PMID 25909164, 2015). "Highly sulfated KS may lead to conformational changes in podoplanin because of negative charges; therefore, immunization with highly sulfated KS-possessing podoplanin is a critical method to induce cancer-specific mAbs against podoplanin." (PMID 25080943, 2014). "Because LpMab-2 reacted with podoplanin-expressing cancer cells but not with normal cells, as shown by flow cytometry and immunohistochemistry, it is an anti-podoplanin CasMab that is expected to be useful for molecular targeting therapy against podoplanin-expressing cancers." (PMID 25080943, 2014).
cancer (continued). "Several putative stem cell markers, such as CD44, CD24, CD166, EpCAM, ABCG2, CD133, and podoplanin, are commonly studied in identifying and isolating the CSCs from the solid tumors; however, subsequent studies demonstrated that the choice of CSC markers differs among cancer originations." (PMID 24804195, 2014). "Further advanced study to understand the pathophysiological functions of podoplanin, including the podoplanin-mediated decreased potential for lymph node metastasis in cancer cells, would provide beneficial information to explore a novel therapeutic strategy for patients with lung SCC." (PMID 21034514, 2010). "Interestingly, transgenic expression of podoplanin in β-cell tumours of Rip1Tag2 mice led to the formation of carcinomas in the absence of a cadherin switch and EMT." (PMID 17179989, 2007). "However, the function of CAF-expressed podoplanin in cancer progression remains unclear, because the overexpression of podoplanin reveals as a negative prognostic factor in some cancers but can have a protective role in others." (PMID 31137693, 2019). "Moreover, expression of podoplanin can be modified by MSC responses to inflammatory mediators, and is often upregulated in inflamed tissues and cancer, where it could contribute to further pathology." (PMID 30745334, 2019). "Interestingly, the podoplanin-mediated resistance of cancer cells to EGFR tyrosine kinase inhibitors depended on its cytoplasmic domain and required direct contact between CAFs and cancer cells, but the molecular mechanism for this effect remains to be elucidated." (PMID 30736372, 2019). "They suggested that these podoplanin negative lesions in the study might have been biopsied before the abnormality developed or the biopsies might have been taken from a different clonal site other than the one in which cancer eventually developed." (PMID 29410757, 2017). "In this article, we will review studies of PDPN in CAT, which together suggest that PDPN contributes not only to cancer progression and metastasis, but also to CAT." (PMID 40741180, 2024). "As Lp2 does not recognize PDPN-expressing normal cells, CAR-T cell therapy based on Lp2 can also be expected to be cancer specific." (PMID 35991754, 2022). "In our experiment with the use of RNA-seq analysis, the expression of podoplanin (PDPN), one of the CAF markers, was detected only in CAFs, but not in either NF monocultures or co-cultures of NFs with cancer cells." (PMID 33143259, 2020). "We have proposed that PDPN is an early-stage CAF marker; however, we did not investigate whether podCAFs promote or suppress cancer progression." (PMID 39451200, 2024). "Furthermore, when IDC cases were divided into two groups: with lymphatic vessel invasion by cancer cells (IDC+) and cases without invasion (IDC-), the podoplanin expression in CAFs was significantly higher in IDC+ than in IDC- cases (p < 0.0001)." (PMID 28938000, 2017). "However it is likely that this medium would have similar effects on the invasiveness of cancer cells as co-culture with CAFs, given the differences in CD10 expression and MMP secretion between PDPN-positive and -negative CAFs." (PMID 24354864, 2013). "While the small number of cancer samples did not allow assessment of statistical significance, several of the new markers identified through mRNA analysis also showed trends of increased protein expression in SQCCs relative to ADCs (CD71/TFRC, CD9, PDPN, CD138/SDC1, CD99)." (PMID 25551685, 2014).
infection (32 papers, 2010 to 2026). The state of being infected such as from the introduction of a foreign agent such as serum, vaccine, antigenic substance or organism. "The incoming monocytes showed a significantly high expression of both CX3CR1 and PDPN on day 2 post-infection." (PMID 39355243, 2024). "The increase in the CX3CR1+PDPN+ F4/80+ macrophage population had statistically significant peaks at day 2, 5 and 16 post LucAdv5 infection." (PMID 39355243, 2024). "The combination of CX3CR1 and PDPN in the myeloid population revealed that the F4/80+ macrophage population showed a significant increase in these two markers throughout the infection phases." (PMID 39355243, 2024). "The cDC2 population included a small subpopulation of CX3CR1+PDPN+ cells, with a small statistically significant decrease from day 2 post-infection to day 23 post-infection." (PMID 39355243, 2024). "Histologic examination of hACE2fl/y lungs 2 and 6 days after infection with SARS-CoV-2 revealed viral nucleocapsid staining primarily along the cell membrane of Podoplanin (PDPN)-positive alveolar type 1 (AT1) epithelial cells." (PMID 36745682, 2023). "Following infection, the PDPN+ reticular network was found to remain intact, excluding the possibility of stromal cell structure damage." (PMID 36317628, 2022). "The result showed that some mesenchymal markers, such as COL1A1, α-SAM, and TAGLN, faded and endothelial markers PROX1 and PDPN increased starting at the fourth day post-infection." (PMID 34936683, 2021). "In the liver, STm infection induces the upregulation of podoplanin in inflammatory foci and podoplanin can bind C-type lectin-like receptor 2 (CLEC-2) that is expressed on platelets and can mediate platelet activation." (PMID 31749809, 2019). "CLEC-2/podoplanin interactions play an important role in thrombosis in the liver after STm infection of mice." (PMID 31749809, 2019). "Our study highlights a new role for platelets in regulating innate immunity during infection through the podoplanin-CLEC-2 axis." (PMID 29269852, 2017). "For this, virions were generated in control and podoplanin knock-down cells, normalized for p24-content and analyzed in trans-infection experiments." (PMID 20482880, 2010). "However, statistically significant increases and peaks in F4/80+PDPN+ cells were observed in this region at day 2 (7.96 ± 2.15%), and day 16 (3.70 ± 1.49%) post-infection." (PMID 39355243, 2024). "PDPN expression among the selected myeloid cell populations showed that several of them had increased expression in the acute phase of inflammation on day 2 post-infection." (PMID 39355243, 2024). "Notably, the migration of LPS-treated HuMoDCs to PDPN-coated wells was also inhibited by LDPm infection." (PMID 37125906, 2023). "Podoplanin levels were unaffected in Prnp0/0 and WT lungs after infection." (PMID 29723291, 2018). "In addition, a significant increase in bleeding within the peritoneal cavity was observed in PDPNfl/flVAVcre+ mice compared to controls, indicating that podoplanin expressed on hematopoietic cells maintains vascular integrity following infection." (PMID 29269852, 2017). "For this, C8166-SEAP cells and PBMCs were infected with a replication-competent HIV-1 variant harbouring EGFP and analyzed for binding of annexin V and the podoplanin-specific antibody 18H5 at seven days post infection, when massive cytopathic effect was visible in infected C8166-SEAP cell cultures." (PMID 20482880, 2010). "However, we note that total LEC numbers in the dLN, as determined by CD31 and PDPN, were reduced during WT CHIKV infection compared with CHIKV 181/25 infection, suggesting that the major changes in LEC subsets are accurate." (PMID 38194268, 2024). "Interestingly, a population of F4/80+ cells expressing both PDPN and CD206 was detected in the normal tissue and increased during inflammation with a significant peak at day 16 post-infection." (PMID 39355243, 2024).